RSAD2 (radical S-adenosyl methionine domain containing 2)
Diseases named in the same sentence as RSAD2 in open-access papers (continued):
Sharing a sentence is not in itself a finding about the gene and the disease.
dermatomyositis (7 papers, 2017 to 2025). Dermatomyositis (DM) is a type of idiopathic inflammatory myopathy characterized by evocative skin lesions and symmetrical proximal muscle weakness. "As a result, M2 macrophages were positively associated with the expression of IFIT3, OAS3, ISG15, and RSAD2 in patients with inflammatory cardiomyopathy and dermatomyositis, respectively." (PMID 37118825, 2023). "This miRNA appears to regulate genes enriched in type I interferon signaling pathways (IFIT3, OAS3, ISG15, and RSAD2), which correlate with increased M2 macrophage infiltration in both dermatomyositis and myocarditis." (PMID 40433545, 2025). "RSAD2 has been reported as the biomarker both in myocardial injury in dermatomyositis and HF, Our study illustrated that RSAD2 was closely associated with the inflammatory response in DCM." (PMID 38321374, 2024). "In one study, ISG15, IFIT3, OAS3, and RSAD2 were prominently enriched in the type I IFN signaling pathway, serving as central hub genes associated with myocarditis-related immune processes, suggesting their potential involvement in the mechanism of myocardial injury in dermatomyositis." (PMID 38753730, 2024).
systemic lupus erythematosus (6 papers, 2020 to 2025). An autoimmune multi-organ disease typically associated with vasculopathy and autoantibody production. "RSAD2 was also the most highly ranked hub gene in a study to identify shared molecular etiologies for pemphigus and systemic lupus erythematosus using WGCNA analysis." (PMID 34997119, 2022). "It has been shown to contribute to pregnancy complications in systemic lupus erythematosus (SLE) by promoting placental lipid accumulation and impairing vascular development, an effect alleviated by the RSAD2 inhibitor L-chicoric acid." (PMID 41267080, 2025). "Similarly, IFIT1 and RSAD2 also have a critical function in lupus development." (PMID 34079550, 2021).
atherosclerosis (5 papers, 2012 to 2025). A disease characterized by the build-up of fatty material and calcium deposition in the arterial wall resulting in partial or complete occlusion of the arterial lumen. "Increased RSAD2 expression has been reported in age-related diseases such as atherosclerosis, the pathology of which is associated with deposition of drusen components such as Aβ and AGE." (PMID 24977103, 2012). "In atherosclerosis, local inflammation could cause increased RSAD2 expression, leading to abnormal lipid accumulation." (PMID 24977103, 2012). "Furthermore, RSAD2 is significantly upregulated in atherosclerosis, and its expression is regulated by pro-inflammatory agents (i.e., lipopolysaccharides, cytomegalovirus, and IFN-γ) but not by tumor necrosis factor α or IL-1β." (PMID 40430829, 2025). "During the process of atherosclerosis, RSAD2 may play a role through inflammatory and immune responses." (PMID 40078458, 2025). "Emerging evidence suggests that RSAD2 may play a role in atherosclerosis, as it interferes with cellular processes that are central in the development and progression of atherosclerosis." (PMID 38589444, 2024). "Combining our findings, we uncover a novel role for RSAD2 in hAoSMCs, which could potentially contribute to monocyte recruitment in the context of atherosclerosis." (PMID 38589444, 2024). "While RSAD2 was reported to be expressed in endothelial cells of human carotid lesions, its significance for the development of atherosclerosis remains utterly unknown." (PMID 38589444, 2024). "Among them, RSAD2, with the most node connections, can induce lipid droplet formation and lipid synthesis, suggesting that the lipid- and atherosclerosis-related pathways may not only be involved in Mφ inflammatory responses but also serve as a key hub for regulating inflammation." (PMID 40572241, 2025). "However, our findings reveal, for the first time, that RSAD2 is also expressed by SMCs and macrophages within carotid atherosclerotic plaques, although its significance for the development of atherosclerosis has remained completely unknown." (PMID 38589444, 2024).
breast carcinoma (5 papers, 2021 to 2025). "Studies show that RSAD2 is up‐regulated and associated with worse relapse‐free survival in breast cancer." (PMID 35810383, 2022). "A bioinformatics study on breast cancer reported that RSAD2 expression was associated with tumor grade, stage, and size." (PMID 34384424, 2021). "Interestingly, increased expression of RSAD2 is associated with worse survival for breast cancer patients, and to our knowledge, the relationship between CSF1 and RSAD2 has not been shown before." (PMID 35406623, 2022). "RSAD2 has already been identified as a significant factor affecting the progression and prognosis of various cancers including colorectal and breast cancer." (PMID 40510586, 2025). "In breast cancer, RSAD2, along with HERC5 and CCL8, was identified as a crucial gene impacting prognosis through gene co-expression network analysis." (PMID 40510586, 2025). "In addition, our analysis identified an IFN-responsive neutrophil population with high expression of IFN-responsive genes (Ifit3, Ifit1, Ifit3b, Ifi47, Ifitm3, Rsad2, Isg15, and Isg20), which is more present in metastatic lung of breast cancer." (PMID 37483625, 2023).
ZIKV infection (5 papers, 2018 to 2025). "Interestingly, cells of neural and placental origin also showed a reduced ISG response during ZIKV infection, compared to poly(I:C) stimulation, with the expression of Viperin/RSAD2 being particularly diminished." (PMID 31652496, 2019). "Interestingly, in opposition to our results, in another study was demonstrated that RSAD2 as wells as IFN response is induced upon ZIKV infection in mice astrocytes; however, RSAD2 regulation and its capacity to restrict viral replication in human astrocytes remain to be investigated." (PMID 33791243, 2021). "ZIKV infection was shown to induce the expression of the ISGs IFIT1-3, RSAD2/Viperin, and OAS1 in primary human DCs." (PMID 31652496, 2019). "During ZIKV infection in this individual, there was similar strong induction of type I ISGs, exemplified by MX1, OAS3, RSAD2, and IFI27 genes (Cluster 2), but minimal coincident induction of chemokines involved in leukocyte chemotaxis (Cluster 1)." (PMID 30596671, 2018).
co-infection (4 papers, 2020 to 2025). "Collectively, these findings establish a robust molecular framework for understanding GV and HPV16 co-infection pathogenesis and highlight IFIT1 and RSAD2 as promising diagnostic biomarkers and therapeutic targets in HPV-related diseases." (PMID 40510586, 2025). "Single-gene GSEA analysis indicates that IFIT1 and RSAD2 regulate multiple biological processes during co-infection." (PMID 40510586, 2025). "This study is the first to find that RSAD2 expression is suppressed in both GV infection and persistent HPV16 infection, suggesting a significant role of RSAD2 in co-infection scenarios." (PMID 40510586, 2025). "The analysis revealed that the interferon-induced genes IFIT1 and RSAD2 play central roles in the pathological process of co-infection." (PMID 40510586, 2025). "Their mature forms, hsa-miR-34a-3p and hsa-miR-654-5p, can directly regulate the expression of IFIT1 and RSAD2, suggesting that they may be non-coding RNA molecules potentially influenced by co-infection and are worth further study." (PMID 40510586, 2025). "Therefore, IFIT1 and RSAD2 are considered key regulatory factors during co-infection." (PMID 40510586, 2025). "The co-expression of RSAD2 and ISG15 during co-infection suggests a coordinated IFN-mediated immune response in the caudal fin." (PMID 40943072, 2025). "In the caudal fin, Mc+ (1 day after co-infection with T. bryosalomne) fish showed mild immune activation with C4B upregulation, while Tb+ fish exhibited a stronger response involving IFI44, ISG15, RSAD2, and TLR7 signaling." (PMID 40943072, 2025). "Our study also highlighted the pivotal role of hub gene RSAD2 and IFIT1 in the context of co-infection." (PMID 40510586, 2025). "To investigate the biological functions and signaling pathways co-regulated by the hub genes IFIT1 and RSAD2 during GV and HPV16 co-infection, we performed GSEA for each gene across both datasets." (PMID 40510586, 2025). "Together, these findings indicate that RSAD2 may play a critical role in cervical cancer triggered by GV and HPV16 co-infection." (PMID 40510586, 2025). "Our study identifies IFIT1 and RSAD2 as key regulators in GV and persistent HPV16 co-infection." (PMID 40510586, 2025). "The co-infection allowed observation of multiple genes involved in the obstruction of the viral life cycle within the host such as MX1,MX2, OASL, OAS2, heat shock protein family A (Hsp70) member 8 (HSPA8), and radical S-adenosyl methionine domain containing 2 (RSAD2)." (PMID 33187194, 2020).
colorectal cancer (4 papers, 2023 to 2025). A primary or metastatic malignant neoplasm that affects the colon or rectum. "Recent research has found that RSAD2 upregulation is present in colorectal cancer and is a prognostic biomarker for immunotherapy." (PMID 40024473, 2025). "In colorectal cancer, RSAD2 is a key component of the tumor immune microenvironment and serves as a prognostic predictor." (PMID 40510586, 2025). "To create an endogenous type I IFN reporter, we chose the colorectal cancer cell line HCT116, which is highly efficient for CRISPR-based gene editing, and surveyed IFNα induction of canonical type I IFN target genes (IFIT1, IFIT2, IFIT3, IFI27, IRF7, OASL, RSAD2)." (PMID 38358346, 2024).
hepatitis C (4 papers, 2007 to 2025). "Functional enrichment analysis revealed that MX1 and RSAD2 were enriched in influenza A and hepatitis C signaling pathways." (PMID 37334926, 2023). "Moreover, KEGG analysis showed that MX1 and RSAD2 were enriched in influenza A and hepatitis C signaling pathways." (PMID 37334926, 2023). "Moreover, MX1 and RSAD2 were enriched in influenza A and hepatitis C signaling pathways." (PMID 37334926, 2023).
HIV-1 infection (4 papers, 2014 to 2024). The type species of lentivirus and the etiologic agent of acquired immunodeficiency syndrome (AIDS). "After HIV-1 infection, upregulation of a cluster of ISGs (RSAD2, ISG15, IFI44L, and IFI27), as compared to pre-SC, emerged and the expression of these ISGs remained high during the untreated course of infection." (PMID 39104769, 2024). "We observed an increase in the levels of various ISGs such as MX1, IFI44L, DDX58, RSAD2, and several of the IFITs, which have been shown to play an important role against HIV-1 infection in MDMs." (PMID 25170834, 2014). "We found that HIV-1 infection induced the expression of a set of ISGs (RSAD2, ISG15, IFI44L, and IFI27) that remained upregulated during the chronic phase of HIV-1 infection." (PMID 39104769, 2024).
ovarian carcinoma (4 papers, 2013 to 2022). A malignant neoplasm originating from the surface ovarian epithelium. "In ovarian cancer, all of the up-regulated genes were increased with more advanced stage (CXCL10, RIPK2 and SPP1) or higher pathological grade (CXCL11, KPNA2, RSAD2, THOC4 and TNC)." (PMID 23536776, 2013).
Primary Sjogren's Syndrome (4 papers, 2021 to 2025). "Silencing RSAD2 in B cells from patients with primary Sjögren’s syndrome attenuates their hyperactivation via suppression of the NF-κB pathway, suggesting its potential as a therapeutic target." (PMID 41267080, 2025). "Finally, we examined this IRG signature (ISG15, SIGLEC1, STAT1 RSAD2, IFI27 and IFI44L) in peripheral blood mononuclear cells (PBMCs) collected from a smaller cohort of healthy controls, disease controls, AAV and primary Sjogren’s syndrome (pSS) patients." (PMID 33859290, 2021).
melanoma (3 papers, 2017 to 2024). A malignant, usually aggressive tumor composed of atypical, neoplastic melanocytes. "To assess the relevance of the innate immune response genes for human melanomas, we used RNA expression data from the TCGA SKCM metastatic melanoma dataset and analyzed the cumulative patient survival in relation to RSAD2 and IFIH1 expression." (PMID 32978520, 2020). "Representative genes from this gene set such as Rsad2, Ifih1, Isg15, Ifit1 and Tmem173 were consistently found to be upregulated in all available NRF2 knockout melanomas." (PMID 32978520, 2020). "Furthermore, genes corresponding to the innate immune response such as RSAD2 and IFIH1 were strongly elevated in absence of NRF2 and coincided with immune evasion parameters in human melanoma datasets." (PMID 32978520, 2020).
myocarditis (3 papers, 2023 to 2025). Myocarditis is a condition that is characterized by inflammation of the heart muscle (myocardium). "We found M2 macrophages increased in DM and myocarditis compared to the healthy control, associating with the expression of IFIT3, OAS3, ISG15, and RSAD2 in DM and myocarditis positively." (PMID 37118825, 2023). "The expression levels of IFIT3, OAS3, ISG15, and RSAD2 were verified in myocardial tissue between myocarditis mice and normal control." (PMID 37118825, 2023). "We finally identified 4 common hub-genes related to the immune process of myocarditis and DM: IFIT3, OAS3, ISG15, and RSAD2." (PMID 37118825, 2023).
polymyositis (3 papers, 2017 to 2023). A rare idiopathic inflammatory myopathy characterized by symmetric proximal muscle weakness and elevated muscle enzymes. "Another study reported that the breakdown of positive IFN-I signatures (top five IFIGs were IFI6, RSAD2, STAT2, IFI44, and IFI27) in whole blood of patients were 73% SLE, 68% SSc, 66% DM, 61% polymyositis (PM), and 33% RA." (PMID 36979843, 2023).
Sepsis (3 papers, 2021 to 2023). Sepsis is defined as life-threatening organ dysfunction caused by a dysregulated host response to infection. "Rsad2 (Radical S-adenosyl methionine domain containing 2) is found to be responsive to interferon and again is found to be associated with the cytokine-induced changes as observed during sepsis." (PMID 35955534, 2022). "RSAD2, a gene associated with antiviral responses, displayed a more restrained expression profile, suggesting its involvement in PANoptosis might be context-dependent within the immune cells of sepsis." (PMID 38239341, 2023). "We observed an upregulation in the expression of IFI44, IFIH1, IFIT1, IFIT2, and RSAD2 in lung tissues from animals suffering from sepsis." (PMID 38239341, 2023). "PCR confirmed the significant upregulation of the genes including ANXA1, SIPR1, EDN1, and RSAD2 in the neutrophils samples from patients with sepsis-induced immunosuppression (at 3–4 days and/or 6–8 days post sepsis shock) compared with controls (P < .05)." (PMID 33761636, 2021). "Similarly, RSAD2’s constrained expression pattern in certain immune cells points to its specific involvement in PANoptosis within the sepsis context." (PMID 38239341, 2023). "Additionally, ZBP1, XAF1, IFI44L, SOCS1, and PARP14 were notably high in HighPANscore cells, aligning with our observations of upregulated expression of IFI44, IFIH1, IFIT1, IFIT2, and RSAD2 in lung tissues from sepsis-induced animal models." (PMID 38239341, 2023).
Aicardi-Goutières syndrome (2 papers, 2019 to 2021). "We next examined baseline gene expression (qPCR) of archetypal interferon stimulated genes (ISGs) IFI27, USP18, MX1, OASL, IRF7, and MX2, and those ISGs found highly expressed in PBMCs from the type 1 interferonopathy, Aicardi-Goutières syndrome (AGS) patients (IFI27, ISG15, IFI44L, and RSAD2)." (PMID 33746960, 2021).
anemia (2 papers, 2022 to 2025). A reduction in the number of red blood cells, the amount of hemoglobin, and/or the volume of packed red blood cells. "The presence of extra-hepatic metastasis, high RSAD2 mRNA gene expression, higher WCC, and anemia were independent poor prognostic factors for OS (p < 0.01)." (PMID 41439936, 2025). "Anemia was seen in nearly half of the SLE patients in this study, and the expression levels of RSAD2, USP18, and IFI44 were lower in those patients." (PMID 35967341, 2022).
avian flu (2 papers, 2015 to 2019). "Also known as viperin, RSAD2 is upregulated in response to H5N1 avian flu and dengue infections through involvement in interferon and cytokine signaling pathways." (PMID 31412766, 2019).
glioblastoma (2 papers, 2021 to 2024). The most malignant astrocytic tumor (WHO grade IV). "Human glioblastoma cells were infected by attenuated MV as a kind of oncolytic virotherapy, which activated RSAD2 expression in tumor cells." (PMID 34403221, 2021).
HCMV infection (2 papers, 2012 to 2023). "Among these candidates, five host factors (PML, Sp100, ISG15, IRP9, and RSAD2) have been related to HCMV infection and were further investigated." (PMID 37058447, 2023). "RSAD2 was amplified as a control for genes specifically upregulated after HCMV infection." (PMID 22607552, 2012).
hepatocellular carcinoma (2 papers, 2018 to 2025). A malignant tumor that arises from hepatocytes. "A clinical study showed supportive evidence that, in resected hepatocellular carcinoma (HCC), RSAD2 gene upregulation had an association with blood vessel invasion, which is a proven risk factor for developing metastasis." (PMID 41439936, 2025). "To this end, we compared the expression of twelve genes either linked to the induction of innate immunity (STAT1, STAT2, PKR) or IFN effector genes (OAS1/2, IFIT1–3, RSAD2, MX1, TRIM14, ISG15) in HCV-infected hepatoma cells and mature iHLCs." (PMID 29497123, 2018).
herpes simplex infection (2 papers, 2019 to 2022). "For the thymus, the NOD-like receptor signaling pathway (PLCB1/MAPK11), the MAPK signaling pathway (SRF/MAPK11), influenza A (RSAD2/MAPK11), and MAPK11 (salmonella, toll-like, herpes simplex infection) were observed." (PMID 30769908, 2019).
malaria (2 papers, 2022 to 2023). Malaria is a serious and sometimes fatal disease caused by a parasite that commonly infects a certain type of mosquito which feeds on humans. "Among the top 50 genes identified in our RNA-Seq experiment, 5 of them (IFNG, CXCL8, IL3RA, SNX10, MYOF, and RSAD2) had promoter regions that were significantly more accessible in convalescent child patients with malaria than in adult convalescent patients." (PMID 35642634, 2022).
mesothelioma (2 papers, 2022 to 2025). A usually malignant and aggressive neoplasm of the mesothelium which is often associated with exposure to asbestos.
neuroblastoma (2 papers, 2017 to 2020). Neuroblastoma (NB) is the most common solid, extracranial childhood tumor. "Similar to the previous findings in Pink1−/− mice, an upregulation of RSAD2 and a downregulation of HEBP1 were observed in the starving PINK1-deficient neuroblastoma cells." (PMID 28768533, 2017). "In contrast to our results, TBEV infection in the human neuronal DAOY cells, a human neuroblastoma, led to upregulation of the RSAD2 gene, a discrepancy that may be due to the use of non-physiological, immortalized cells in the study in question." (PMID 32127025, 2020). "In neuroblastoma cells, the poly(I:C) triggered inductions were significantly blunted by PINK1 knockdown for RSAD2, DDX58, IFIT3, and IFIT1." (PMID 28768533, 2017).
Obesity (2 papers, 2019 to 2021). Accumulation of substantial excess body fat. "Genotype-phenotype correlations in obese mice using ATR-FTIR spectroscopy has shown that Rsad2 is associated with obesity-related diseases." (PMID 31882756, 2019). "Interestingly, adipose tissue expression of Rsad2 is increased in obesity and its genetic ablation results in decreased fat mass due to increased thermogenesis." (PMID 34294678, 2021).